ABCB11 (ATP binding cassette subfamily B member 11)
Diseases named in the same sentence as ABCB11 in open-access papers (continued):
Sharing a sentence is not in itself a finding about the gene and the disease.
cholestasis (continued). "We recently described an association between genetic predisposition for cholestasis with a polymorphism in the gene coding for the bile salt export pump (BSEP; ABCB 11 1331C allele) and non-sustained virological response (SVR) in a HCV patient cohort." (PMID 30507970, 2018). "For example, inhibition of the bile salt export pump (BSEP/ABCB11) at the canalicular membrane of hepatocytes may lead to cholestasis; inhibition of OATP1B1 and OATP1B3 at the basolateral membrane of hepatocytes may lead to hyperbilirubinemia." (PMID 28272367, 2017). "Genetic defects in ATP8B1 or ABCB11 account for the majority of cholestasis with low GGT." (PMID 27050426, 2016). "Drug-induced cholestasis can be replicated as exemplified by treatment with chlorpromazine resulting in significant downregulation of ABCB11, encoding the bile acid transporter BSEP, and a marked accumulation of intra-cellular bile acids." (PMID 27754327, 2016). "In light of this strong effect, these studies have important implications, not just for genetic factors that affect maternal bile acid levels, but also environmental factors such as drugs that produce cholestasis secondary to inhibition of bile acid transporters (for example, ABCB11)." (PMID 26416771, 2015). "Individuals with variants in ABCB11 rarely develop cholestasis until BSEP function drops below a threshold, which is also influenced by other factors (e.g., drugs, hormones); AOCDs, such as DIL or ICP, can develop when BSEP function falls below the approximate 25% threshold." (PMID 39984942, 2025). "The mechanism by which elevated hepatic phytosterol levels cause cholestasis likely involves the interruption of Farnesoid X receptor (FXR) signaling and subsequent downregulation of the canalicular bile acid transporter, bile salt export pump (BSEP;ABCB11;31see below)." (PMID 40015320, 2025). "Recent literature report that cholestasis may also be related to mutations in genes encoding bile acid metabolic transporters such as ABCB11, ABCB4, ABCCC2, ATP 8B1, TJP2, which result in the abnormal function of bile salt export pump in hepatocytes." (PMID 38191339, 2024). "In addition, some missense mutations in less conserved regions of the ABCB11 and ABCB4 genes promote the development of more moderate variants of cholestasis such as BRIC2, ICP, cholesterol cholelithiasis, drug-induced cholestasis, adult biliary cirrhosis, transient neonatal cholestasis, and others." (PMID 35740260, 2022). "In contrast to patients with cholestatic liver disease related to ABCB11 mutations, functional analysis of ABCB11 deficiency in rodents showed that ABCB11 deficient mice did not develop progressive cholestasis and were associated with a milder phenotype when compared to MDR2 deficient mice." (PMID 31886153, 2019). "No exact results show the association between ABCB11 SNPs with cholestasis liver injury." (PMID 29221149, 2017). "Recent studies suggested that additional mutations in ABCB11 may be associated with various disease processes such as benign recurrent intrahepatic cholestasis (BRIC), intrahepatic cholestasis of pregnancy (ICP), and risk for drug-induced cholestasis (DC)." (PMID 25392597, 2014). "Interestingly, hepatic overexpression of Abcb11 reduced hepatic lipids, indicating that the markedly reduced Abcb11 expression could contribute not only to cholestasis but also to the observed increase in liver triglycerides." (PMID 23700488, 2013). "Many drugs have the potential to block ABCB11 (bile salt export pump, BSEP), the pump responsible for bile salt extrusion into the canaliculi, leading to cholestasis or drug-induced liver injury (DILI)." (PMID 39204140, 2024). "Here, we reviewed the leading molecular pathways between the DIC and ABCB1, ABCC2, ABCB11, and ABCB4 genes, the links with the other clinical forms of familial intrahepatic cholestasis, and, finally, the main cholestasis-inducing drugs." (PMID 36982896, 2023).
cholestasis (continued). "Ursodeoxycholic acid (UDCA), used as a treatment for patients with cholestasis, was also shown to stimulate the targeting of ABCC2 and ABCB11 transporters to the plasma membrane." (PMID 33672718, 2021). "The key role of canalicular ABC transporters in bile secretion is highlighted by their implication in a wide range of diseases such as cholestasis (ABCB4, ABCB11), sitosterolemia (ABCG5/G8), Dubin–Johnson syndrome (ABCC2) and cancer (ABCB1)." (PMID 33672718, 2021). "Mechanistically, IL-1β appears to mediate cholestasis in PNAC through hepatocellular NF-κB signaling, which interferes with the ability of FXR to bind to and transactivate Abcb11 and Abcc2 promoters, thus reducing canalicular bile and bilirubin transport." (PMID 29643332, 2018). "Hepatic mRNA expression of Abcb11 and Abcc2 was suppressed in DSS/PN mice at 3 days, preceding evidence of cholestasis and hepatocyte injury, and were progressively suppressed by 14 days." (PMID 29643332, 2018). "Elevated serum bile acids and bilirubin in the face of transcriptional suppression of Abcb11 and Abcc2 therefore strongly implicate insufficient expression of BSEP and MRP2 in the pathogenesis of cholestasis in this model." (PMID 29643332, 2018). "Important genes known to play a role in cholestasis such as ABCB4 (MDR3), ABCB11 (BSEP) and NR0B2 (SHP) were downregulated in human PCLS exposed to bile acids and cholestatic drugs." (PMID 27344345, 2017). "Treatment with 4-PB of six patients with PFIC2 carrying the G982R, R1128C, T1210P, R1231Q, and the Y157C/G1298R variations of ABCB11 and of one BRIC2 patient carrying the D404G variation resulted in a decrease in cholestasis." (PMID 40508041, 2025). "L-Cas9Tg/Tg mice injected with AAV8 sgRNA targeting Abcb11 showed hepatomegaly and cholestasis without histological evidence of liver injury." (PMID 38517206, 2024). "Expression of Abcb11 was initially decreased in several rodent models after endotoxin or ethinylestradiol exposure and after CBDL, but recovery may occur with prolonged cholestasis." (PMID 34774795, 2021). "Thereby, immunohistochemical assessment of ABCB11 and ABCB4 may be useful to determine the degree of cholestasis as well as the disease progression in PSC patients." (PMID 31886153, 2019). "Levels of the bile salt export pump (BSEP/Abcb11) were not decreased in combined steatosis and cholestasis compared to cholestasis, while levels of multidrug resistance-associated protein 2 (MRP2/Abcc2) were (p < 0.05)." (PMID 27535001, 2016). "Another mechanism of toxicity could be the inhibition of the activity of the bile salt export pump (BSEP or ABCB11), which is responsible for cholestasis." (PMID 20981297, 2010). "However, as illustrated by other studies, GGT levels alone may not reliably differentiate between cholestasis linked to ABCB4 and ABCB11 variants, since some ABCB4 variants may not show elevated GGT levels." (PMID 41436587, 2025). "However, unlike what happens for mutations in ABCB11, the inhibition of MDR3 in biliary phospholipid excretion may represent a risk factor for drug-induced cholestasis, although BA secretion is not altered." (PMID 36982896, 2023).
intrahepatic cholestasis (46 papers, 2010 to 2025). A cholestasis characterized by impairment of the bile flow caused by obstruction located in the liver. "Cases were defined as participants with rare (minor allele frequency <1%) heterozygous loss of function (LoF) variants in ABCB4 and ABCB11 (genotype re-call) or with a previous intrahepatic cholestasis of pregnancy (ICP) diagnosis (ICD10 O26.6)." (PMID 41436587, 2025). "55.6% of participants with rare heterozygous ABCB4/ABCB11 variants or a history of intrahepatic cholestasis of pregnancy showed evidence of liver involvement, highlighting the utility of genetic screening and monitoring." (PMID 41436587, 2025). "For example, a transient course of neonatal intrahepatic cholestasis is frequent among carriers of predicted biallelic pathogenic variants in ABCB11, which was resolved upon improved expression of BSEP." (PMID 36015138, 2022). "In line with this, loss-of-function variants in the FXR-encoding gene NR1H4 also cause intrahepatic cholestasis associated with the loss of ABCB11 expression." (PMID 33557414, 2021). "The expression of Abcb11 was markedly reduced in the Fxr deficient mice and reduced function or expression of Abcb11 results in a clinical syndrome of intrahepatic cholestasis." (PMID 23700488, 2013). "Therefore deficiency of ATP8B1 might result in dysfunction of transmembrane transporters such as ABCB11, the bile salt export pump, within the canalicular membrane of liver cells, causing intrahepatic cholestasis." (PMID 24260417, 2013). "ABCB11 (coding BSEP) gene mutations are implicated in cholestatic disorders including progressive familial intrahepatic cholestasis type 2 (PFIC-2), intrahepatic cholestasis, and DILI." (PMID 40776909, 2025). "Among the various genetic subtypes, mutations in the ABCB11 gene can lead to a deficiency of the bile salt export pump (BSEP), leading to intrahepatic cholestasis." (PMID 37361697, 2023). "Liver biopsies of patients with intrahepatic cholestasis and MYO5B variants revealed a reduced expression and partial mislocalization of ABCB11, and in some cases also of ABCC2 and ABCB4." (PMID 33557414, 2021). "Several studies have proposed that the PPARγ agonist troglitazone induces intrahepatic cholestasis via the inhibition of ABCB11, potentially contributing to hepatotoxicity." (PMID 24799887, 2014). "Our patient was found to have two variants associated with intrahepatic cholestasis: a likely pathogenic variant (ACMG class 4) in the ABCB11 gene, linked to PFIC2, and a variant of uncertain significance (ACMG class 3) in the ATP8B1 gene, which is associated with PFIC1." (PMID 41395309, 2025). "In addition to PFIC1 and -2, benign recurrent forms of intrahepatic cholestasis (termed BRIC) and intrahepatic cholestasis of pregnancy have also been associated with ATP8B1 and ABCB11 mutations." (PMID 33557414, 2021). "Data from The Netherlands suggest that rifampicin may be a more appropriate therapy for individuals with ABCB11 mutations associated with clinical BSEP deficiency and Benign Recurrent Intrahepatic Cholestasis (BRIC) outside of pregnancy." (PMID 33435904, 2021). "BRIC is an autosomal recessive disorder caused by the mutation of two hepatic transporter genes: the ATP8B1 gene, coding for familial intrahepatic cholestasis-1 (FIC1; BRIC type 1) and the ABCB11 gene, coding for the bile salt export pump (BSEP; BRIC type 2)." (PMID 23403701, 2013). "Estrogen can decrease the expression of ABCB11 / BSEP gene to inhibit the function of bile salt delivery pump, or decrease the activity of Na+ / K+ ATPase to inhibit the uptake of bile acid by hepatocytes that eventually leads to intrahepatic cholestasis." (PMID 33028282, 2020). "While the molecular events in the livers of these patients are unknown, this clinical setting is consistent with our model in which statin-induced miR-33 represses both ABCB11 and ATP8B1, thus decreasing bile secretion and eventually leading to intrahepatic cholestasis." (PMID 22767443, 2012).
progressive familial intrahepatic cholestasis type 2 (42 papers, 2009 to 2025). Progressive familial intrahepatic cholestasis type 2 (PFIC2), a type of progressive familial intrahepatic cholestasis (PFIC), is a severe, neonatal, hereditary disorder in bile formation that is hepatocellular in origin and not associated with extrahepatic features. "Progressive familial intrahepatic cholestasis type 2 (PFIC2) is a rare pediatric cholestatic liver disease caused by genetic deficiency in the bile salt export pump (BSEP, ABCB11)." (PMID 40513781, 2025). "Biallelic mutations in the ABCB11 gene lead to progressive familial intrahepatic cholestasis type 2 (PFIC2), an inherited autosomal recessive liver disease." (PMID 38341604, 2024). "Mutations or adverse drug reactions affecting ABCB11 can result in diseases such as progressive familial intrahepatic cholestasis type 2 (PFIC2) and drug-induced cholestasis (DIC)." (PMID 39770445, 2024). "Mutation of the ABCB11 gene encoding BSEP induces BSEP deficiency and progressive familial intrahepatic cholestasis type 2 (PFIC2)." (PMID 28150711, 2017). "Importantly, ABCB11 has been associated with type 2 Progressive Familial Intrahepatic Cholestasis, which is a severe human genetic disease." (PMID 38731931, 2024). "Progressive familial intrahepatic cholestasis type 2 (PFIC2) is a severe hepatocellular cholestasis due to biallelic variations in the ABCB11 (ATP-binding cassette B11) gene encoding the canalicular bile salt export pump (BSEP)." (PMID 40508041, 2025). "Progressive familial intrahepatic cholestasis type 2 (PFIC2) is an ultra-rare disease caused by mutations in the ABCB11 gene." (PMID 38341604, 2024). "For example, inherited deficiency of ABCB11 due to gene mutations can result in progressive familial intrahepatic cholestasis type 2 (PFIC2)." (PMID 35741809, 2022). "Genetic alterations in the ABCB11 gene can cause a severe form of liver disease, progressive familial intrahepatic cholestasis type 2 (PFIC2)." (PMID 28365738, 2017). "Progressive Familial Intrahepatic Cholestasis type 2 (PFIC2), the most severe phenotype associated with ABCB11/BSEP deficiency, is a rare autosomal recessive disease with a frequency estimated at around 1/100,000 births." (PMID 40508041, 2025). "Progressive familial intrahepatic cholestasis type 2 (PFIC2), also known as bile salt export pump (BSEP) deficiency disease, is a rare autosomal recessive inherited liver disease caused by mutations in the ABCB11 gene (located on chromosome 2q24-31), leading to impaired bile secretion." (PMID 40520990, 2025). "Both progressive familial intrahepatic cholestasis type 2 (PFIC2) and benign recurrent intrahepatic cholestasis (BRIC2) are caused by mutations in the ABCB11 gene, which encodes the BSEP protein." (PMID 37324459, 2023). "Deficiency of the bile salt export pump (BSEP), also known as progressive familial intrahepatic cholestasis type 2 (PFIC2), is a rare disease that results from mutations in the ABCB11 gene." (PMID 36687469, 2023). "Mutations in the ABCB11 gene, which encodes the BSEP transporter, can cause progressive familial intrahepatic cholestasis type 2 (PFIC2)." (PMID 30023358, 2018).
liver disease (32 papers, 2011 to 2025). "As previously noted, it is well established that heterozygous variants in ABCB4 and ABCB11 can result in milder forms or late-onset liver disease in adults." (PMID 40870862, 2025). "Biallelic loss-of-function variants in ABCB11 result in severe pediatric-onset liver disease, with many patients developing malignancies or pathological complications within the first decade of life." (PMID 37601975, 2023). "Jaundice from intrahepatic cholestatic jaundice of pregnancy (ICP) is a common liver disease during the second and third trimester that can arise from mutations in the ABCB11 gene encoding the bile salt export pump (BSEP)." (PMID 28923092, 2017). "Variations in the ABCB11 gene cause a spectrum of rare liver diseases." (PMID 36142670, 2022). "This review will thus explore how three genes that are associated with liver disease in childhood (ABCB11, TJP2 and VPS33B) might play a role in the initiation and progression of HCC." (PMID 36010647, 2022). "PFIC2, which is caused by mutations in the ABCB11 gene, often progresses to end-stage liver disease." (PMID 41395309, 2025). "Out of the 9 cases, 4/9 (44.4%) had a known diagnosis of metabolic dysfunction associated steatotic liver disease (MASLD) of whom 3/4 (75%) had an ABCB4 LoF and 1/4 (25%) had an ABCB11 LoF variant." (PMID 41436587, 2025). "Mutations in the bile salt export pump (BSEP, ABCB11) the multidrug resistance protein 3 (MDR3, ABCB4) cause progressive familial intrahepatic cholestasis (PFIC) types II and III, respectively (severe cholestatic liver diseases appearing in early infancy)." (PMID 31597297, 2019). "ABCB11 is one of the liver disease related genes and its activity is affected by Troglitazone." (PMID 22401035, 2012). "Immunostaining of ABCB11 and Rab11a in liver biopsies from patients with Myosin 5b defects demonstrated abnormal distribution of these proteins, suggesting that mislocalization of ABCB11 due to abnormal trafficking could be responsible for the liver disease, at least in this subgroup of MVID." (PMID 26116792, 2015). "In contrast, in adult patients with primary sclerosing cholangitis, ABCB11 was significantly overexpressed compared with other cholestatic and noncholestatic liver diseases, but these were patients with well-established liver disease." (PMID 34774795, 2021). "For instance, PFIC and BRIC are both typically caused by biallelic mutations in ATP8B1 or ABCB11; however, patients with BRIC do not exhibit the severe liver disease seen in patients with PFIC." (PMID 34828443, 2021). "Here we show that, in PSC patients, ABCB11 and ABCB4 are significantly overexpressed when compared to other cholestatic and noncholestatic liver diseases." (PMID 31886153, 2019). "The aim of this study was to investigate the expression and localization of the critical bile transporters ABCB11 and ABCB4 in liver tissue samples from patients with different types of chronic cholestatic and noncholestatic liver disease, with particular emphasis on PSC." (PMID 31886153, 2019). "Therefore, ABCB11 and ABCB4 expressions were investigated on formalin-fixed and paraffin-embedded (FFPE) material in a patient cohort of total 43 patients with or without cholestatic liver diseases, on protein level using immunohistochemistry and on RNA level using nanoString technology." (PMID 31886153, 2019).
Cholestatic liver disease (21 papers, 2012 to 2026). "Genes involved in bile formation, such as ABCB4 (encodes canalicular phosphatidylcholine floppase) and ABCB11 (encodes bile salt export pump (BSEP)) have been associated with cholestatic liver disease 8–10." (PMID 41436587, 2025). "The protein expression level of BSEP can vary among patients with cholestatic liver diseases due to mutations in the ABCB11 gene." (PMID 37324459, 2023). "In some patients, benign variants (single nucleotide polymorphisms (SNP)) described to predispose to cholestatic liver disease could be detected in heterozygous status, e.g., ABCB11 variant c.1772A>G, p.(Asn591Ser) or ABCB11 variant c.1331T>C, p.(Val444Ala)." (PMID 37761392, 2023). "Tauroursodeoxycholate (TUDC), which is a frequently used drug for cholestatic liver disease in humans, was shown to stimulate the mobilization of ABCB11 from sub-canalicular compartments to the canalicular plasma membrane." (PMID 33557414, 2021). "Genetic analysis using next-generation sequencing included a panel of five genes involved in cholestatic liver diseases (ATP8B1, ABCB11, ABCB4, ABCC2 and MYO5B)." (PMID 41797682, 2026). "In contrast, the staining pattern of ABCB11 and ABCB4 was mostly consistent in all PSC patients, when compared to patients with other chronic liver/cholestatic liver diseases." (PMID 31886153, 2019). "Therefore, we investigated in this study ABCB11 and ABCB4 on RNA as well as protein levels in liver tissue of patients with different types of cholestatic liver diseases, with a special interest in PSC." (PMID 31886153, 2019). "It thus appears that the intracellular trafficking of ABCB11 and other canalicular proteins, and in particular the involvement herein of RAB11A-positive ARE, plays a pivotal role in the regulation of canalicular function and, when perturbed, in cholestatic liver disease." (PMID 33557414, 2021). "Increased expression of ABCB11 and ABCB4 was very consistent in PSC patients and not observed in other cholestatic liver diseases." (PMID 31886153, 2019).